POLR1C (RNA polymerase I and III subunit C)
Diseases named in the same sentence as POLR1C in open-access papers:
POLR1C is named in the same sentence as 35 diseases in open-access papers, as found by Europe PMC text mining. Sharing a sentence is not in itself a finding about the gene and the disease. The quoted sentences say what the papers report.
leukodystrophy (22 papers, 2015 to 2024). Leukodystrophies are a group of rare, progressive, metabolic, genetic diseases that affect the brain, spinal cord and often the peripheral nerves. "This study aimed to investigate the clinical, radiological, and genetic features of POLR3-related leukodystrophy caused by mutations in POLR3A or POLR1C." (PMID 38550343, 2024). "Recently, novel POLR1C mutations were reported in two Korean siblings with ataxia and leukodystrophy." (PMID 35685919, 2022). "POLR3A or POLR3B mutations cause the majority of POLR3-related leukodystrophy cases, with POLR1C mutations accounting for approximately 5% of cases." (PMID 35685919, 2022). "Mutations in the POLR1C gene have been reported to cause leukodystrophy, hypomyelinating-11, and an autosomal recessive disease (OMIM# 616494)." (PMID 35685919, 2022). "Leukodystrophy due to POLR1C mutation is exceptionally rare; so far, only 26 such patients have been reported worldwide." (PMID 33804237, 2021). "Our findings provided a definitive genetic diagnosis reinforcing the association between POLR1C mutations and hypomyelinating leukodystrophy and highlighted the relevance of multi-omics approaches to the disease." (PMID 33804237, 2021). "Altogether, the results obtained reinforce the association between POLR1C mutations and hypomyelinating leukodystrophy as well as the importance of multi-omics approaches to disease." (PMID 33804237, 2021). "Clinical and radiological characteristics of our case were compatible with hypomyelinating leukodystrophy due to mutations on the POLR1C gene." (PMID 33804237, 2021). "More recently, recessive mutations in POLR1C have been found to cause leukodystrophy, or degeneration of white matter in the brain, and interestingly, these mutations alter POLR1C function specifically as a part of RNA Pol III." (PMID 27448281, 2016). "Leukodystrophy associated mutations in POLR1C perturb Pol III assembly and occupancy at Pol III promoters but not Pol I assembly or occupancy at the rDNA promoter." (PMID 27448281, 2016). "In conclusion, our sequencing study of 18 cases with compatible clinical and/or radiological features with 4H or POLR3-related leukodystrophy identified 13 different POLR1C mutations in eight cases." (PMID 26151409, 2015). "Our study using the WES technique helped in disease diagnosis and elucidated that the variant in the POLR1C gene may play an important role in the development of leukodystrophy and hypomyelinating disease in the Saudi family." (PMID 35685919, 2022). "Mutations in the genes encoding the components of POLR1C can result in leukodystrophy." (PMID 35685919, 2022). "Finally, our study explained the important use of WES in disease diagnosis and provided further evidence that the variant in the POLR1C gene may play an important role in the development of hypomyelinating leukodystrophy in Saudi families." (PMID 35685919, 2022). "In the last few years, our group has identified and validated eight genes causative for leukodystrophy, including POLR3A, POLR3B, POLR1C, POLR3D, EPRS1, VARS1, and ABHD16A." (PMID 39062571, 2024). "POLR3-related leukodystrophy is caused by biallelic pathogenic variants in genes encoding subunits of Pol III, i.e. POLR3A, POLR3B, POLR1C and POLR3K." (PMID 36451185, 2022). "Recently, a multicenter retrospective study including 150 patients with 4H leukodystrophy demonstrated that 56 (37.3%) patients carried the mutations in POLR3A, 81 (54%) in POLR3B, and 13 (8.7%) in POLR1C." (PMID 36042647, 2022). "The POLR1C gene encodes for the RNA polymerase I and III subunit C, and the variants found have already been associated with TCS and hypomyelinating leukodystrophy." (PMID 33804237, 2021). "A total of 150 patients with 4H leukodystrophy and pathogenic variants in POLR3A, POLR3B, or POLR1C were included." (PMID 33005949, 2021).
leukodystrophy (continued). "4H leukodystrophy has been found to be caused by biallelic pathogenic variants in POLR3A, POLR3B, POLR1C, and POLR3K, each of which encode subunits of the POLR3 complex." (PMID 33005949, 2021). "4H or POLR3-related leukodystrophy is an autosomal recessive disorder typically characterized by hypomyelination, hypodontia, and hypogonadotropic hypogonadism, caused by biallelic pathogenic variants in POLR3A, POLR3B, POLR1C, and POLR3K." (PMID 33005949, 2021). "Mutations in genes encoding subunits of the transcription complex RNA polymerase III (POLR3), namely POLR3A, POLR3B, POLR1C, POLR3K and POLR3GL might cause a particular type of hypomyelinating leukodystrophies known as Pol III-related leukodystrophies." (PMID 33804237, 2021). "We reported on a Spanish patient with POLR1C hypomyelinating leukodystrophy." (PMID 33804237, 2021). "In addition, an ever-increasing number of distinct mutations in the POLR3A, POLR3B, POLR1C and POLR3K subunits cause a spectrum of neurodegenerative diseases, which includes most notably hypomyelinating leukodystrophy." (PMID 34395528, 2021). "4H or POLR3-related leukodystrophy is inherited in an autosomal recessive fashion and is caused by mutations in one of three genes encoding RNA polymerase III (POLR3) subunits, that is, POLR3A, POLR3B, and POLR1C." (PMID 26478204, 2017). "At the time of the initial clinical exome analysis, neither PMPCA nor POLR1C were associated with spinocerebellar ataxia and leukodystrophy, respectively." (PMID 28327206, 2017). "To compare the roles of leukodystrophy versus TCS-causing mutations in the biogenesis of POLR1 and POLR3, we expressed FLAG-tagged POLR1C with the p.Arg279Gln (R279Q) mutation in HeLa cells, affinity-purified the tagged subunit and identified the purified interactors using mass spectrometry." (PMID 26151409, 2015). "POLR3-HLD, also termed 4H (Hypomyelination, Hypodontia, and Hypogonadotropic Hypogonadism) leukodystrophy, is caused by biallelic pathogenic variants in genes encoding subunits of the ubiquitous RNA polymerase III (Pol III) enzymatic complex (e.g., POLR3A, POLR3B, POLR1C, POLR3K, and POLR3D)." (PMID 39062571, 2024). "Both missense variants found at POLR1C—a gene that encodes a subunit common to RNA polymerases I (POLR1) and III (POLR3)—affect amino acids that are conserved through species, and have been known to be associated with Treacher Collins syndrome (TCS) and hypomyelinating leukodystrophies." (PMID 33804237, 2021). "Our assessment of the precursor stage suggested migration was unaffected when Polr3a, Polr3b, or Polr1c were downregulated, proposing that failure of OPCs to migrate to myelination sites is unlikely to explain the hypomyelination seen in POLR3-related leukodystrophy." (PMID 37179550, 2023). "POLR1C is a common subunit of both RNA polymerase I (POLR1) and POLR3, which selectively alters the availability of both enzymes, resulting in two separate clinical conditions: Treacher Collins syndrome and POLR3-related leukodystrophy." (PMID 35685919, 2022). "Using shotgun proteomics and ChIP sequencing, we demonstrate that leukodystrophy-causative mutations, but not TCS mutations, in POLR1C impair assembly and nuclear import of POLR3, but not POLR1, leading to decreased binding to POLR3 target genes." (PMID 26151409, 2015). "However, similar to POLR1C, recessive mutations in POLR1D have also been identified in association with TCS, but to date none of these have been linked to leukodystrophy." (PMID 27448281, 2016).
Treacher-Collins syndrome (21 papers, 2012 to 2026). A congenital disorder of craniofacial development characterized by bilateral symmetrical oto-mandibular dysplasia without abnormalities of the extremities, and associated with several head and neck defects. "Craniofacial abnormalities reminiscent of Treacher Collins syndrome have been originally described in patients with POLR3-HLD caused by biallelic pathogenic variants in POLR1C." (PMID 37197783, 2023). "Pathogenic variants in the TCOF1 but also the POLR1D and POLR1C genes have been previously associated with Treacher Collins syndrome (TCS) types 1–3, respectively." (PMID 33262786, 2020). "Seven similar nonsense mutations, detected in cancer tissues, are listed in the Ensembl database (GRCh37, release 82), and dysfunctions in POLR1C activity are associated with Treacher Collins syndrome." (PMID 27341347, 2016). "Treacher Collins syndrome is associated with mutations of POLR1C and POLR1D (OMIM 248390 and OMIM 613717), and hypomyelinating leukodystrophy is associated with mutations of POLR3A and POLR3B (OMIM 607694 and OMIM 614381)." (PMID 24040563, 2013). "Mutations in POLR1C were recently shown to cause Treacher Collins syndrome and PKHD1 mutations are associated with polycystic kidney and hepatic disease and were thus excluded as candidate genes for PD." (PMID 22563501, 2012). "Furthermore, we have established polr1c and polr1d mutant zebrafish as models of Treacher Collins syndrome together with a unifying mechanism underlying its pathogenesis and possible prevention." (PMID 27448281, 2016). "For instance, pathogenic variants in two subunits of RNA polymerase III, POLR1C and POLR1D, were previously linked to Treacher-Collins syndrome (MIM#248390, #613717)." (PMID 40229899, 2025). "More specifically, mutations in POLR1A cause Acrofacial Dysostosis Cincinnati type (AFDCin), whereas mutations in POLR1B, POLR1C and POLR1D and the Pol I associated protein, TCOF1/TREACLE lead to Treacher Collins Syndrome (TCS)." (PMID 37639467, 2023). "One study that includes 252 individuals with Treacher Collins syndrome (TCS3; 248390) was done, and the three patients with compound heterozygous mutations in the POLR1C gene were identified." (PMID 35685919, 2022). "Treacher Collins syndrome (TCS) is caused by various mutations in the genes TCOF1, POLR1B, POLR1C, or POLR1D." (PMID 36271492, 2022). "Consistent with this pattern of activity, polr1c and polr1d homozygous mutant zebrafish exhibit cartilage hypoplasia and cranioskeletal anomalies characteristic of humans with Treacher Collins syndrome." (PMID 27448281, 2016). "Transcription of the ribosomal RNAs (rRNAs) by RNA polymerases (Pol) I and III, is considered a rate limiting step of ribosome biogenesis and mutations in the genes coding for RNA Pol I and III subunits, POLR1C and POLR1D cause Treacher Collins syndrome, a rare congenital craniofacial disorder." (PMID 27448281, 2016). "Mutations in genes encoding the two RNA Pol I subunits, POLR1C and POLR1D, and in the nucleolar protein Treacher Collins-Franceschetti syndrome 1 (TCOF1, also known as treacle) cause the craniofacial disorder, Treacher Collins syndrome (OMIM 248390, OMIM 613717 and OMIM 154500)." (PMID 24040563, 2013). "The identification of causative mutations in the TCOF1 gene (85% of the cases), but also in the RNA polymerase I (Pol I) subunits POLR1C, POLR1D and recently, POLR1B strongly suggests that perturbation of ribosome biogenesis is the underlying cause of Treacher Collins Syndrome." (PMID 35646927, 2022).
Treacher-Collins syndrome (continued). "The genetic link of Treacle, POLR1C, POLR1D, and POLR1B to Treacher Collins Syndrome (TCS) in humans strongly indicates that disturbance of ribosome biogenesis is linked to the development of the disease." (PMID 35646927, 2022). "Treacher Collins syndrome has been proven to be genetically heterogeneous, and three genes (TCOF1, POLR1D, and POLR1C) have been identified in the etiology of TCS." (PMID 32543076, 2020). "Notably, several genes involved in the craniofacial-biased disease Treacher Collins syndrome, TCOF1, POLR1C, and POLR1D, were low-scoring genes found to be expressed at high levels in virtually all tissues (Gini scores 0.23, 0.19, and 0.15 respectively)." (PMID 37532691, 2023). "Of note, POLR1C was described in 2011 to cause recessive Treacher Collins syndrome (MIM 248390), however the patient’s clinical features were not matching those of Treacher Collins syndrome, potentially complicated by the blended phenotype due to the dual molecular diagnosis." (PMID 28327206, 2017).
Ataxia (4 papers, 2017 to 2022). Ataxia refers to impaired coordination of voluntary muscle movement. "However, the patient exhibited several neurological phenotypes consistent with POLR1C mutations, including hypomyelination, ataxia, and nystagmus, but the patient’s other clinical features are not described in POLR1C-related cases." (PMID 33134290, 2020).
gastric cancer (3 papers, 2016 to 2024). A primary or metastatic malignant neoplasm involving the stomach. "POLR1C was reported as one of the ten most up-regulated proteins when infiltrative gastric cancer regions were compared to the adjacent normal tissue." (PMID 38790250, 2024). "These hub genes such as SRC (Proto-Oncogene C-Src), DNM1L (Dynamin 1-Like) and POLR1C (polymerase (RNA) I polypeptide C) are critical downstream effectors of CEACAM6 in gastric cancer progression." (PMID 29137373, 2017).
4H leukodystrophy (1 paper, 2022). "4H leukodystrophy, one of POLR3-related leukodystrophy, is a rare hereditary brain white matter disease caused by the pathogenic biallelic variations in POLR3A, POLR3B, or POLR1C." (PMID 36042647, 2022).
Brugada syndrome 5 (1 paper, 2017). Any Brugada syndrome in which the cause of the disease is a mutation in the SCN1B gene. "In another family, quad WES analysis identified a paternally inherited heterozygous missense variant of unknown significance in SCN1B, the gene for Brugada syndrome 5 (MIM 612838), and compound heterozygous changes in POLR1C, segregating in two affected siblings." (PMID 28327206, 2017).
ciliopathy (1 paper, 2022). A genetic disorder of the cellular cilia or the cilia anchoring structures, the basal bodies, or of ciliary function. "Overall, the results of the bioinformatic analysis, segregation analyses, clinical phenotype coherence, and ciliopathy coherence supported that the homozygous variant of POLR1C was the causative variant of the patient, which was first reported." (PMID 35685919, 2022).
Epileptic encephalopathy (1 paper, 2025). A condition in which epileptiform abnormalities are believed to contribute to the progressive disturbance in cerebral function. "Representative examples include POLR1C (RNA polymerase dysfunction), TCF4 (Pitt–Hopkins syndrome), and HNRNPU (epileptic encephalopathy)." (PMID 41300846, 2025).
esophageal cancer (1 paper, 2022). A primary or metastatic malignant neoplasm involving the esophagus. "The effect of circular RNA-RNA polymerase I and III subunit C (circPOLR1C) on esophageal cancer (EC) has not been reported." (PMID 36590309, 2022).
H1N1 influenza (1 paper, 2017). "For H1N1 influenza, 2 DNBs (IRF7, POLR1C) are also observed in the cytosolic DNA-sensing pathway." (PMID 28835768, 2017).
microphthalmia (1 paper, 2016). Congenital or developmental anomaly in which the eyeballs are abnormally small. "Although overall body size is comparable between mutant embryos and control siblings, polr1c-/- and polr1d-/- mutants present with a considerably smaller head together with mandibular hypoplasia and microphthalmia." (PMID 27448281, 2016).
Myoclonus (1 paper, 2024). Very brief, involuntary random muscular contractions occurring at rest, in response to sensory stimuli, or accompanying voluntary movements. "Severe cases of myoclonus have also been associated with other variants including those in the POLR1C gene." (PMID 39436788, 2024).
cancer (4 papers, 2014 to 2024). A tumor composed of atypical neoplastic, often pleomorphic cells that invade other tissues. "Importantly, basal cancers express high mRNA levels of genes encoding regulators of ribosome biogenesis such as BYSL, RRS1, RIOK1, POLR1C, and POLR1E (group C)." (PMID 32054925, 2020).
tumor (4 papers, 2022 to 2025). "For instance, POLR1C (polymerase (RNA) I polypeptide C, 30 kDa) had the largest up-regulation in both cell culture lines even as its expression level was not significantly changed in the malignant part of the surgically removed tumor (x(T) = −1.09; x(Φ) = 198.71; x(Θ) = 221.73)." (PMID 38790250, 2024).
neurodevelopmental disorder (1 paper, 2025). A behavioral and cognitive disorder with onset during the developmental period that involves impaired or aberrant development of intellectual, motor, or social functions. "Group 1—Severe multisystem neurodevelopmental disorders (Transcriptional/RNA-processing phenotype): This group included patients carrying variants in POLR1C, TCF4, HNRNPU, NIPBL, and ACTG1." (PMID 41300846, 2025).
POLR1C also shares sentences with these, for which no sentence is quoted: hypogonadotropic hypogonadism (4 papers); breast carcinoma (2); colon cancer (2); Hypodontia (2); acrofacial dysostosis (1); acrofacial dysostosis Cincinnati type (1); branchiootic syndrome 1 (1); cartilage-hair hypoplasia (1); choanal atresia (1); Diamond-Blackfan anemia (1); glioblastoma (1); hepatic disease (1); mandibulofacial dysostosis (1); microtia (1); neurodegenerative disease (1); Nystagmus (1); polycystic kidney (1); Shwachman-Diamond syndrome (1); Treacher Collins syndrome 3 (1); X-linked dyskeratosis congenita (1).